IDH1 (isocitrate dehydrogenase (NADP(+)) 1)
Diseases named in the same sentence as IDH1 in open-access papers (continued):
Sharing a sentence is not in itself a finding about the gene and the disease.
glioma (continued). "IDH1 mutations can be found in nearly 90% of low-grade gliomas, and more than 90% of IDH1 mutations contain an arginine-to-histidine switch at position 132 (IDH1R132H)." (PMID 33767690, 2020). "The most common IDH1 mutations in glioma (> 95%) result in an amino acid substitution at arginine 132 (R132), which resides in the enzyme’s active site." (PMID 31960234, 2020). "An induction in H3K9me3 and H3K27me3 is also observed in glioma samples harbouring an endogenous IDH1 mutation." (PMID 31728625, 2020). "The purpose of this study is to investigate the relationships between IDH1 mutation and MRI features as well as prognosis in patients with glioma." (PMID 32582544, 2020). "IDH1/2 mutations proved independent prognostic factors in glioma and associated with MGMT methylation for better survival." (PMID 33552543, 2020). "DNA sequence evaluation of the IDH2 exon in glioma samples revealed that all the nine somatic mutations were at residue R172: The R172 residue in IDH2 is the exact analog of the R132 residue in IDH1." (PMID 33552543, 2020). "IDH1 mutation detection was confirmed in plasma ctDNA of 80 glioma patients with 100% specificity and 60% sensitivity." (PMID 32650387, 2020). "In the present study, we retrospectively analysed MET-PET/CT and FLT-PET/CT in newly diagnosed gliomas for differentiating glioma according to the 2016 WHO classification especially in relation to IDH1 mutation status." (PMID 32382870, 2020). "About 50% of MMP-producing cells in the infiltration zone and 68–82% in the solid portion of the tumors were IDH1-mutated glioma cells." (PMID 32872536, 2020). "For example, adult low-grade astrocytomas and the higher grade gliomas which arise from malignant progression often possess IDH1 or IDH2 gene mutations." (PMID 32375301, 2020). "IDH1/2 mutations are observed in 60–90% of lower grade gliomas (59–88% in diffuse astrocytomas and 68–82% in oligodendrogliomas) and in 10% of GBMs." (PMID 32570988, 2020). "In this study, SR-FTIR has been used to examine human brain glioma tissue, where single-point spectra have been collected from tissue microarray (TMA) sections comprising IDH1-mutated and IDH1-wildtype glioma tissue cores." (PMID 33302429, 2020). "As key drivers of tumorigenesis in diverse cancers, such as glioma, cholangiocarcinoma, and leukemia, IDH1/2 mutations have been the foci of a number of experimental and clinical studies." (PMID 32587392, 2020). "In 2016 WHO classification, codeletion of chromosomal arms 1p/19q (1p/19q codeletion) and isocitrate dehydrogenase 1 or 2 (IDH1 or IDH2) were included in diagnostic typing for glioma classification." (PMID 33330074, 2020). "We proposed a novel deep learning-based method to predict the IDH1/2 mutation status in a glioma, even prior to IDH1 immunohistochemistry (which is typically performed using an antibody against the R132H mutation) and/or genetic sequencing." (PMID 32382048, 2020). "Recent studies have examined MET uptake for differentiating glioma based on the 2016 WHO classification especially in relation to IDH1 mutation and 1p/19q codeletion status." (PMID 32382870, 2020). "A limited number of cancer types (e.g., glioma, acute myeloid leukemia and chondrosarcoma) harbor frequent mutations in IDH1 and IDH2 genes, among which iCCA is one." (PMID 32824685, 2020). "This is the case of mutations in IDH1 or IDH2 in lower-grade gliomas, and histone 3 (H3F3A and HIST1H3B) mutations in pediatric high-grade gliomas that are also associated with specific patterns of DNA methylation." (PMID 31968687, 2020). "There was a main R132H mutation site within the IDH1 gene, which was predominantly presented in the ectoderm-derived brain lower-grade glioma." (PMID 33308219, 2020). "Herein, we evaluated tracer uptakes of MET-PET/CT and FLT-PET/CT for differentiating glioma based on the 2016 WHO classification especially in relation to IDH1 mutation status." (PMID 32382870, 2020).
glioma (continued). "This study showed that FLT-PET/CT can be used to determine the IDH1 mutation status and evaluate glioma grade more accurately than MET-PET/CT." (PMID 32382870, 2020). "This study found the overall survival period of IDH1 mutated glioma was significantly different from that of IDH1 wild-type glioma." (PMID 32582544, 2020). "It should be noted that IDH1/2 mutation is the most frequent mutant type of gliomas and can be detected by either DNA sequencing or IHC methods." (PMID 32293336, 2020). "Mutation status of IDH, including IDH1, is a distinctive biomarker for glioma classification and prognostic assessment." (PMID 33425739, 2020). "Simultaneously, another study showed that D2-HG, produced by glioma cells with the IDH1 mutation, contributes to malignant progression of gliomas." (PMID 32993063, 2020). "Patients with wild type IDH1 gliomas had an OS of 22.63 months (STD 17.67), while for the mutated IDH1 group it was 38.33 (STD 29.73), p-value = 0.016." (PMID 32050461, 2020). "The overall survival between IDH1 mutated and wild type glioma were significantly different (p = 0.000), age ≤ 40 (p = 0.003), KPS scores > 80 before operation (p = 0.000) and low grade glioma (p = 0.000)." (PMID 32582544, 2020). "DZIP3 classified IDH1 wild-type lower-grade glioma into GBM-like and IDH1 mutation lower grade-like groups with similar survival tendencies." (PMID 33229627, 2020). "In GBM and glioma cases carrying IDH1 mutations, SOCS1 and SOCS3 methylation was increased and their expression was downregulated." (PMID 32931454, 2020). "IDH1 mutation in glioma leads to the loss α-KG and accumulation of 2HG, resulting in genome-wide histone and DNA methylation alterations." (PMID 32051553, 2020). "Using mutated IDH1 as a distinct identifier of glioma cells, we here showed for the first time that glioma cells and not microglia are the definitely predominant producers of MT-MMPs in diffuse glioma." (PMID 32872536, 2020). "The integrated phylogenies advance our knowledge of the complex evolution and immense mutational load of IDH1-mutant HM glioma." (PMID 32904945, 2020). "Grade IV glioma patients with IDH1 mutation had a median overall survival of 46.9 (95% CI: 38.2–55.5) months compared to 50.2 (95% CI: 46.5–53.9) months for those who tested negative (p = 0.22)." (PMID 32005184, 2020). "These include the mutation of the Isocitrate Dehydrogenase 1 and 2 genes (IDH1/2), the codeletion status of chromosome arms 1p and 19q, and histone 3 mutational status, able to distinguish biologically and clinically glioma behaviour." (PMID 32411235, 2020). "Collectively, these results suggest that a combined alteration in membrane lipid metabolism and STAT3 pathway promotes IDH1-mutated glioma malignant progression." (PMID 32218467, 2020). "Although they were successful in generating and testing glioma cells derived from patients, the efficiency for mutated IDH1 was low in comparison to LGG with IDH1 wt56." (PMID 33221817, 2020). "The lowest quartile of TET1 expression is significantly associated with glioma hazard in a multivariate model of TET1 + age + IDH1 status + Histological type." (PMID 32483272, 2020). "Patients with IDH1 mutated glioma were reported to be younger than patients with wild-type IDH1 gene." (PMID 32856857, 2020). "It was shown that TINs were dramatically decreased in gliomas samples harboring IDH-1 mutations (p < 0.001)." (PMID 32756015, 2020). "Peptide vaccination resulted in efficient mutation-specific antitumor immunity in the mouse model with IDH1 R132H-mutated gliomas." (PMID 33228738, 2020). "We then analyzed the expression of GPR133 across glioma molecular subtypes, as defined by the IDH1/2 mutations, 1p19q codeletion, and BRAF status." (PMID 32642706, 2020). "IDH1/2 mutations have been detected in many human cancers, including glioma, chondrosarcoma, acute myeloid leukemia, and cholangiocarcinoma." (PMID 32293336, 2020).
glioma (continued). "Fifty-nine grade II/III glioma patients with known IDH1 mutation status were prospectively included (IDH1 wild type, 16; IDH1 mutation, 43)." (PMID 32153362, 2020). "IDH1 mutation has been shown to have diagnostic, prognostic, and predictive value with regard to gliomas." (PMID 33247679, 2020). "High BACE2 expression was related to wild‐type IDH1 in glioma patients, while low BACE2 expression was associated with other features, including MGMT promoter methylation, 1p/19q codeletion, TERT loss and ATRX mutation." (PMID 31856384, 2020). "This is the case for a subset of human gliomas characterized by mutations in the IDH1 gene, which codes for the NADP-dependent cytosolic IDH1 enzyme." (PMID 33083024, 2020). "After the introduction of the 2016 WHO classification, IDH1/2 mutation status was key for classifying glioma patients." (PMID 33214617, 2020). "Several lines of evidence have demonstrated that mutation of IDH1 indicates enhanced chemosensitivity and is associated with an improved prognosis in glioma patients." (PMID 32038986, 2020). "This is comparable to urine 2HG concentrations for gliomas with IDH1/2 mutations (1–14.6 ng/mL), which were found to be much higher than for gliomas with wt IDH1/2 (1–4 ng/mL)." (PMID 31847543, 2020). "IDH1/2 mutated gliomas have a better prognosis due to their slow proliferating rate and aggressiveness, again cancer metabolism seems to play a role." (PMID 32993063, 2020). "The molecular definition of WHO grade IV gliomas makes distinctions based on IDH1 mutation and 1p19q co-deletion status." (PMID 32355162, 2020). "Based on the presence of pTERT mutations, IDH1/2 mutations, and 1p/19q codeletion status, gliomas were divided into five subtypes with different overall survival." (PMID 33643908, 2020). "Mutations in IDH1/2 genes are a marker of good prognosis for glioma patients, associated with low grade gliomas and secondary glioblastomas." (PMID 29556922, 2019). "The TCA cycle has been implicated as a potential therapeutic target in IDH1-mutant gliomas and our observation that the TCA cycle is compromised in IDH1R132H cells supports this possibility." (PMID 31888244, 2019). "Mutations in the isocitrate dehydrogenase-1 gene (IDH1) occur at high frequency in grade II–III gliomas (LGGs)." (PMID 31240524, 2019). "In the context of solid tumors, 5-azacytidine induced tumor regression in glioma xenograft models obtained from patients with the IDH1 mutation." (PMID 31163702, 2019). "Elevated D-2-HG levels impact prognosis and therapy of patients with mutated IDH1/2 tumours like glioma or AML." (PMID 31092874, 2019). "Although many new molecular markers have been identified, the IDH1 mutation remains the most stable, and is widely used in glioma studies." (PMID 31824866, 2019). "The UPDB resource allowed us to evaluate the association between the rs55705857 G allele and several types of IDH associated cancers in relatives of individuals with IDH1/2 mutated glioma." (PMID 30823903, 2019). "In IDH mutated gliomas, elevated D-2-HG levels were induced by the gain-of-function of the mutant IDH1 protein." (PMID 31242696, 2019). "High-throughput DNA sequencing of human gliomas identified mutually exclusive somatic mutations in either IDH1 or IDH2 in approximately 70% of secondary glioblastomas and grade II–III gliomas." (PMID 31105869, 2019). "IDH1 R132H mutant gliomas famously exhibit a glioma-associated CpG island methylator phenotype (or G-CIMP), which arises from the competitive inhibition of DNA-demethylating TET proteins by the oncometabolite 2-HG30." (PMID 31439867, 2019). "IDH1 mutations are known to be a favorable prognostic marker of LGGs and more enriched in grade II gliomas compared to grade III gliomas." (PMID 31861486, 2019). "In the primary SOX2 high expression gliomas, 2 cases had IDH1 mutation, their PFS and OS were both longer than the medium level (PFS: 20 & 13.5 months; OS: 49.5 & 57.0 months)." (PMID 31718604, 2019).
glioma (continued). "In the 2016 WHO classification, detection of IDH1 mutation in a tumor resembling a ganglioglioma strongly supported the diagnosis of an infiltrating glioma with ensnared neurons." (PMID 30984614, 2019). "It has been shown that 2-HG inhibits α-KG-dependent dioxygenases such as methylcytosine dioxygenase (TET2), which leads to the CpG island-methylator phenotype (G-CIMP) prevalent in gliomas with IDH1/2 mutations." (PMID 31888244, 2019). "Several reports pointed out that prognosis for glioma patients with the IDH1 mutation is associated with DNA methylation patterns." (PMID 30857299, 2019). "IDH2 mutant gliomas have a higher level of 2-HG/tCho (total choline=phosphocholine+glycerylphosphorylcholine) (2.48 ± 1.01vs.0.72 ± 0.38, Pc < 0.001) and myo-Inositol/tCho (2.70 ± 0.90 vs. 1.46 ± 0.51, Pc = 0.011) compared to IDH1 mutation gliomas." (PMID 30791611, 2019). "Recently, genome wide association studies have consistently identified the rs55705857 G allele at 8q24 as a risk factor for gliomagenesis that is specific for IDH1/2 mutated gliomas." (PMID 30823903, 2019). "The IDH1 p.R132H mutation is found primarily in lower grade glioma, and found in 42% of these tumors." (PMID 31440245, 2019). "Gliomas with Isocitrate dehydrogenase 1 (IDH1) mutation have alterations in several enzyme activities, resulting in various metabolic changes." (PMID 31278288, 2019). "Those resources offering mainly pediatric data-sets do hardly include higher numbers on mutations within IDH1 while in adult samples the mutated gene is known to be connected to glioma." (PMID 30675185, 2019). "There is ample evidence that IDH1 mutation alone is insufficient to initiate glioma formation in vivo." (PMID 31652645, 2019). "Further work will be needed to investigate possible epigenetic effects of an IDH1 mutation on genes which are involved in the organization of the actin cytoskeleton IDH1R132H-expressing glioma cells." (PMID 31242696, 2019). "In this regard, the presence of IDH1 mutations in gliomas is known to be a predictor of improved outcome." (PMID 31428936, 2019). "Deep learning-based radiomics (DLR) was developed on a dataset of 151 patients with low-grade glioma with multiple modalities of magnetic resonance (MR) images for predicting the mutation status of IDH1, and achieved ACC of 0.91 and AUC of 0.96." (PMID 30616515, 2019). "Given that IDH1/2 mutations are early observed events in several cancers such as glioma, chondrosarcoma and AML, selective inhibitors targeting IDH 1/2 mutation are attractive strategies for cancer therapy." (PMID 31151327, 2019). "The most common IDH1 mutation in gliomas (IDH1 R132) occurs in the catalytic domain of IDH1 and confers the ability to produce 2-hydroxyglutarate (2-HG)." (PMID 31806013, 2019). "This system distinguishes different subtypes of low‐ and of high‐grade glioma based on mutations in isocitrate dehydrogenase 1 (IDH1), and codeletion of the short arm of chromosome 1 and the long arm of chromosome 19 (1q/19p)." (PMID 30667110, 2019). "Gene expression in IDH1-mut mouse gliomas was negatively associated with leukocyte and neutrophil migration." (PMID 30857299, 2019). "ODH3 mutation of IDH1/2 is found in low-grade glioma and secondary glioblastoma (GBM), chondrosarcoma, intrahepatic cholangiocarcinomas, hematologic malignancies, premalignant diseases, and rare inherited metabolism disorders." (PMID 31817761, 2019). "When IDH1 or IDH2 is mutated in gliomas (most frequently at codon R132 or R172, respectively), the mutated protein gains a neomorphic enzymatic activity, and produces D-2-hydroxyglutarate (2-HG) from α-ketoglutarate (α-KG)." (PMID 31652645, 2019). "In gliomas, mutations of the cytosolic IDH1, most frequently occurring heterozygous IDH1 R132H point mutation, are much more common than mutations of the mitochondrial homolog IDH2." (PMID 31652645, 2019).
glioma (continued). "One hundred and two individuals with IDH1/2 mutant or 1p/19q co-deleted glioma were genotyped and linked to the UPDB." (PMID 30823903, 2019). "Consistent with this, introduction of IDH1 mutation or exogenous 2-HG in syngeneic mouse glioma models reduces the levels of CTL-attracting and IFN-gamma-inducible chemokines, including CXCL10." (PMID 31652645, 2019). "Another important mechanism that associates chromatin modifications with DNA methylation is directly related to 2HG production in IDH1/2 mutated gliomas." (PMID 31311166, 2019). "MRE demonstrated that gliomas were not only softer than normal brain, but the degree of softening was directly correlated with tumor grade and IDH1 mutation status." (PMID 31242696, 2019). "In the HGG group, ITSS grades of IDH1-mutated gliomas were significantly lower than those of Wild-type gliomas (p < 0.01)." (PMID 31745161, 2019). "In the diagnosis of gliomas, immunohistochemistry and genomic sequencing are considered “gold standard” pathological and molecular methods for detecting IDH1 mutations." (PMID 31275753, 2019). "It has been counterintuitive for a driver mutation as IDH1-mutated gliomas showed a favorable OS, in contrast to IDH1-mutated acute myeloid leukemia with a poor prognosis." (PMID 31443404, 2019). "While in gliomas, IDH1/2 mutations are associated with favorable outcome, in other solid tumors and leukemia the effect on prognosis is either less favorable or unclear." (PMID 31727977, 2019). "Mutations in the isocitrate dehydrogenase enzyme (IDH1), specifically the R132H mutation, almost exclusively occur in gliomas and other cancers of the central nervous system." (PMID 32039009, 2019). "The levels of cis-aconitic acid and isocitric acid, components of TCA cycle, in glioma samples with IDH1 mutation were comparable with those in IDH1 normal glioma samples compared with other components of TCA cycle." (PMID 31278288, 2019). "Further studies have found that the IDH1 R132H mutation is the most common mutation in gliomas, while the IDH2 gene also undergoes similar mutations at R172, but the frequency of such mutations are relatively low." (PMID 31263678, 2019). "They synthesized neopeptides containing IDH1 (R132H) p123-142 mutated region to bind to transgenic human MHC-II molecules in glioma mouse model." (PMID 31492199, 2019). "The IDH1 mutation causes the accumulation of 2HG, which decreases the ability of gliomas to repair DNA." (PMID 31450721, 2019). "Meanwhile, old drugs for other tumors have also been developed to treat glioma with IDH1/2 mutations, such as azacitidine, nivolumab, and temozolomide." (PMID 31263678, 2019). "Sex, age, WHO tumor grade, and IDH1 mutation status were all included in the final model since all four characteristics are well validated prognostic factors in glioma." (PMID 31091655, 2019). "Natural Killer cell ligands and subsequent tumor cell lysis has also been shown to be reduced in IDH1-mutated gliomas." (PMID 31781488, 2019). "Gliomas are now characterized based on the presence of mutations in the isocitrate dehydrogenase family of genes (IDH1 and IDH2)." (PMID 30823903, 2019). "More interestingly, all patients diagnosed with ITSS grade 0 gliomas showed IDH1 mutations and MGMT promoter methylation." (PMID 31745161, 2019). "Lastly, there is an ongoing phase 1 study looking at IDH305 in patients with diverse IDH1 mutation-harboring malignancies, including glioma, AML/MDS, and other solid tumors (ClinicalTrials.gov NCT02381886)." (PMID 31165048, 2019).